INS (insulin)
Diseases named in the same sentence as INS in open-access papers (continued):
Sharing a sentence is not in itself a finding about the gene and the disease.
Insulin resistance (continued). "Augmented activity of the mTOR complex could promote an inability of β-cells to release insulin through an inhibitory effect on the mentioned kinase, leading to cellular insulin resistance and contributing to the development of type 2 diabetes." (PMID 34829598, 2021). "In another study, DNMT3b downregulation in ATMs was found to promote an anti-inflammatory state and enhanced insulin sensitivity, revealing the contribution of DNMT3b-mediated methylation at the Pparg promoter to increased inflammatory conditions and insulin resistance." (PMID 34638914, 2021). "Clinical trials show that insulin administered intranasally is a promising drug to treat neurodegenerative diseases, but at high doses its use may result in cerebral insulin resistance." (PMID 34769198, 2021). "Though this interaction needs further investigation, it may be partly explained by the fact that type 2 diabetic patients who were on insulin might have experienced poor glycemic control probably due to insulin resistance." (PMID 34424924, 2021). "ASTX may reduce hyperglycemia and improve insulin resistance and insulin secretion by the improvement of glucose dysmetabolism and beta-cell dysfunction via GLUT4 regulation." (PMID 34959932, 2021). "However, insulin resistance shows that increased phosphorylated insulin response substract-1 S302 (pIRS-1 S302) and that reduced phosphorylated Akt S473 (pAkt S473), was found in KO mice." (PMID 33931731, 2021). "While most data derived from animal studies confirm the co-existence of metabolic and microvascular insulin resistance, whether factors that predict metabolic insulin resistance also predict microvascular responses to insulin in humans remains less clear." (PMID 34075130, 2021). "Furthermore, glycogenolysis was enhanced, suggesting that glycogen can become a source for glucose due to a reduced insulin-dependent glucose uptake typical of HFD-induced insulin resistance." (PMID 33925229, 2021). "As a result, any disturbance in its expression or function could disrupt insulin signaling and results in insulin resistance." (PMID 34660812, 2021). "For example, the accumulation of visceral WAT is associated with an increased risk of insulin resistance, type 2 diabetes, dyslipidemia, and atherosclerosis, while subcutaneous WAT is associated with higher insulin sensitivity and a reduced risk of type 2 diabetes." (PMID 34371916, 2021). "The possible reason is that T2DM patients with impaired insulin metabolism may experience higher insulin secretion or higher insulin resistance." (PMID 34970224, 2021). "Furthermore, established high-fat diet- (HFD-) induced insulin-resistant mouse models revealed that uterine insulin resistance beginning before pregnancy deteriorated uterine receptivity and decreased implantation sites and fetal numbers." (PMID 33953835, 2021). "Striking features of type 2 diabetes are insulin resistance and insulin secretion reduce." (PMID 34026064, 2021). "Importantly, Crtc1–/– mice displayed insulin resistance but normal lipid levels compared to Crtc1+/+ mice at 8 months old, indicating that insulin sensitivity is earlier than plasma lipid profiles to sense fat accumulation." (PMID 33912553, 2021). "The noted reductions in insulin dose were thought to imply improved insulin resistance." (PMID 33828529, 2021). "The fasting blood glucose, plasma insulin, homeostasis assessment model of insulin resistance (HOMA-IR), glycated hemoglobin (HbA1c), low-density lipoprotein (LDL)-cholesterol, triglycerides, and free fatty acids were similar between the CHF and control groups." (PMID 33500450, 2021). "Whether BCAAs are a causative factor in insulin resistance and T2DM or just a biomarker of impaired insulin action requires further study." (PMID 35046891, 2021).
Insulin resistance (continued). "While this works to reduce hyperglycemia in these patients, the idea of treating a disease of insulin resistance by increasing insulin may be counterproductive, leading to the requirement of increasing amounts of medication over a long period of time." (PMID 33531076, 2021). "In our analysis, only markers of insulin resistance (insulin concentration and HOMA-IR), but not glucose, were associated with selenium in the fully adjusted model." (PMID 34262926, 2021). "Other related studies have also verified that several components in C. chinensis improve follicular developmental disorders, ovulatory disorders, and lower fasting blood glucose and fasting insulin levels to reduce insulin resistance in women with PCOS, concurring with the current study." (PMID 34457027, 2021). "In summary, we found that IR-61 treatment could enhance insulin signal transduction and alleviate insulin resistance in the obese mice." (PMID 33397994, 2021). "However, HFD and corticosterone act synergistically to promote severe insulin resistance beyond the adaptive capacity of beta cells, resulting in impaired insulin response to glucose and hyperglycemia in a longer run." (PMID 33435513, 2021). "Moreover, the presence of pro-inflammatory cytokines impairs insulin signaling, further leading to insulin resistance, among others." (PMID 34069293, 2021). "The finding that microbiota transfer from healthy lean donors to patients with insulin resistance improves the insulin sensitivity of the recipients and the number of butyrate producing bacteria indicates that gut microbiota are involved crucially in insulin signaling and the development of obesity." (PMID 33504065, 2021). "Indeed, the fasting insulin levels observed in all Avy groups were very high (reaching values as high as 15 ng/mL in Avy mice), which is consistent with a severe insulin resistance state." (PMID 34088954, 2021). "The infiltration of immune cells in tissues affected by insulin fluctuations may in part contribute to the increased levels of insulin resistance in COVID-19 patients, as this may result in hyperglycemia that in turn affects disease severity." (PMID 35053020, 2021). "Findings that both DLK1-null and DLK1-overexpressing transgenic mice develop insulin resistance and glucose intolerance also indicate that proper development of adipose tissue function might be critical for maintaining glucose/insulin homeostasis." (PMID 34540403, 2021). "Interestingly, ghrelin has also been proposed to modulate insulin secretion, to prevent insulin resistance and to contribute to glucose handling." (PMID 34831029, 2021). "The coffee bean and its extracts may also have indirect effects in preventing EC, since it inhibits insulin production, improves insulin resistance and so is beneficial to EC patients because it prevents weight gain and modulates glucose metabolism." (PMID 33946913, 2021). "The insulin-related signaling pathways are insulin resistance and insulin signaling pathways." (PMID 34335798, 2021). "Insulin resistance is a state of impaired responsiveness to insulin action." (PMID 33708999, 2021). "Previous studies have indicated that insulin participates in the metabolism of glucose and lipids, and insulin resistance could reduce glucose consumption in the cells and induce abnormal lipid levels." (PMID 34136157, 2021). "Therefore, women with insulin resistance to GDM are likely to benefit from insulin sensitization therapy, providing a new approach for the individualized treatment of GDM." (PMID 34301212, 2021). "Thus, HDAC3 can affect insulin secretion, glucose tolerance, lipotoxicity, insulin resistance, and inflammation in pancreatic cells via multiple mechanisms." (PMID 34301918, 2021). "GDM is characterized by insulin resistance and impaired insulin secretion." (PMID 34721291, 2021).
Insulin resistance (continued). "In addition, insulin resistance and free fatty acid level decreased in the soy group, showing an improvement in hyperglycemia and insulin sensitivity." (PMID 34239993, 2021). "Brain insulin resistance can be defined as a failure of brain cells to respond to insulin." (PMID 34539357, 2021). "Prolonged sedentary activity has been associated with greater insulin resistance, lack of insulin sensitivity, impaired microvascular function and increased overall morbidity and mortality." (PMID 33289502, 2021). "On the other hand, it has been shown both in animal models and humans that insulin resistance and diabetes may be efficiently counteracted by K-ATP channel openers, like diazoxide, which inhibits β-cell insulin secretion." (PMID 32767274, 2021). "Although there is a debate about the fundamental cause of T2DM, in general, insulin resistance is thought to precede its deficiency in the early stages of onset, and hyperglycemia develops when the relative lack of insulin exceeds the threshold." (PMID 35392577, 2021). "However, peripheral insulin resistance, and subsequent chronic hyperinsulinemia, could reduce the transport of insulin through the brain–blood barrier, which was in line with our findings that elevated fasting insulin and insulin resistance were associated with worse cognition." (PMID 34966358, 2021). "Insulin resistance and endothelial dysfunction are linked by changes in the balance between the PI3-K/Akt and MAPK/ERK pathways, explaining the high risk of atherothrombosis in insulin-resistant states." (PMID 33804680, 2021). "Insulin resistance is a state in which insulin-responsive tissue (skeletal muscle, liver, adipose depots) fails to properly respond to physiological insulin levels, and it is strongly associated with obesity." (PMID 34299048, 2021). "The pathological progression of insulin resistance involves the induction of multiple stress-responsive avenues, resulting in cells dysfunction, autophagy, apoptosis, or death in pancreatic β cells that are important to glucose/insulin regulation." (PMID 34885698, 2021). "However, sit-to-stand transitions have been shown to increase postural blood flow and positively impact insulin and homeostatic model assessment of insulin resistance (HOMA-IR)." (PMID 33983131, 2021). "We used the whole-body insulin sensitivity index (WBISI) to represent insulin resistance." (PMID 34485526, 2021). "Thus, improving insulin responsiveness of visceral fat has been regarded as an effective way to alleviate insulin resistance." (PMID 34917687, 2021). "The disease owes to the relative lack of insulin mainly caused by insulin resistance (IR) in fuel storage organs, e.g., skeletal muscles, liver, and white adipose tissues." (PMID 34805244, 2021). "Another animal model with obese Zucker rats also showed that LWDHW could delay insulin resistance and increase insulin sensitivity." (PMID 34457016, 2021). "Since adiponectin exhibits insulin-sensitizing properties, reduced levels of adiponectin may contribute to systemic insulin resistance in women with PCOS." (PMID 34071499, 2021). "Of note, we calculated insulin sensitivity/resistance both at fasting (insulin resistance: HOMA-IR) and during the OGTT (insulin sensitivity: PREDIM), since they may describe somehow different physiological processes." (PMID 34395456, 2021). "In the present study, we investigated this hypothesis that ASK1‐mediated insulin signalling pathway may play an important role in liver ameliorating insulin resistance in obese rats and aimed at providing basic experimental evidence for clinical practice." (PMID 34734480, 2021). "Serum insulin change seemed to reflect the status of β‐cell function and/or insulin resistance." (PMID 34542937, 2021). "However, adipose tissue insulin resistance also leads to reduced inhibition of lipolysis by insulin, which results in elevated free fatty acid (FFA) levels in the blood." (PMID 33387681, 2021).
Insulin resistance (continued). "Interestingly, there have recently appeared studies on the role of the amygdala in insulin resistance, for example, in relation to eating behavior, as well as on the molecular mechanisms of insulin effects in this brain structure." (PMID 34769018, 2021). "Maternal LQP and LP diets enhance insulin sensitivity at the early stages of growth in the offspring, and may pave the way for insulin resistance in later stages." (PMID 34836384, 2021). "Second, SGLT2 inhibitors mitigate insulin resistance in insulin target tissues." (PMID 33802741, 2021). "It has been shown that TCF7L2 is associated with reduced insulin levels rather than increased insulin resistance." (PMID 34073870, 2021). "Furthermore, in a subgroup of participants with type 2 diabetes, the Med diet reduced fasting plasma glucose, insulin and markers of insulin resistance at 24 months to a greater extent compared with the low-fat diet." (PMID 33919503, 2021). "Insulin resistance may also be the result of abnormal adipocyte function, as four nights of sleep restriction resulted in approximately 30% reduction in cellular insulin signaling in adipocytes." (PMID 34779405, 2021). "It is believed that pre-pregnancy decreased maternal insulin sensitivity and pre-conception insulin resistance, impaired insulin response observed during pregnancy, and dysfunction of insulin-producing β-cells are the pathophysiological background of GDM development." (PMID 34836042, 2021). "For instance, a glucose clamp may be used to assess insulin resistance in diabetic mice before and after insulin treatment." (PMID 34917687, 2021). "In this regard, it has been shown that deficiency of IRF7, a master regulator of IFN-I induction, prevents high fat diet (HFD)-induced obesity and insulin resistance pointing to the involvement of this factor in diet-induced alterations in energy metabolism and insulin sensitivity." (PMID 33430520, 2021). "However, further studies are needed to determine the exact mechanism of the chemicals in these seeds on insulin secretion and insulin resistance in diabetic individuals." (PMID 34540481, 2021). "Finally, TMAO induction of insulin resistance was more directly measured by reduced expression of the insulin signaling cascade including insulin receptor substrate 2 (IRS2), PI3K, RAC-β serine/threonine-protein kinase (AKT) and glucose transporter 2 (GLUT2)." (PMID 34445033, 2021). "HFD also induced insulin resistance with higher insulin levels." (PMID 33957965, 2021). "The cinnamic acid derivative not only abolished the previously induced insulin resistance in 3T3-L1 adipocytes but also significantly increased the insulin-stimulated glucose uptake in insulin-resistant 3T3-L1 adipocytes, which significantly outstripped the response of the control cells." (PMID 34684619, 2021). "Moreover, M1 and M2 macrophages in adipose tissues have opposing effects on insulin responses in that M1 macrophages promote insulin resistance whereas M2-macrophages enhance insulin sensitivity." (PMID 33828532, 2021). "Exposure to IH induces systemic insulin resistance and alters the insulin signaling pathway in the main metabolic organs (i.e., adipose tissue, liver, and skeletal muscle); however, the cardiac impact of this IH‐induced insulin resistance remains unclear." (PMID 33682327, 2021). "Insulin can cross the blood–brain barrier into the brain, regulating energy homeostasis, cognition and behavior, and pilot studies suggest a functional relationship between AD and brain insulin resistance." (PMID 34356628, 2021). "A previous study reported that intraperitoneal injection of AMF exerts body weight-lowering effects and protection against HFD-induced metabolic dysfunction by reducing fasting glucose, insulin, homeostasis model assessment of insulin resistance (HOMA-IR), and TG levels in HFD-fed rats." (PMID 33671428, 2021).
Insulin resistance (continued). "In contrast, type 2 diabetes is characterized by combination of peripheral insulin resistance and dysfunctional insulin secretion by pancreatic beta cells, which results in high but inappropriately low circulating insulin concentrations for the level of glycemia." (PMID 34830886, 2021). "Future studies investigating the combined effects of several of these insulin-related miRNAs may provide avenues for combating multiple aspects of central insulin resistance." (PMID 34831343, 2021). "The mild hypoinsulinemia in the βOgtOE Hz may have contributed to the trend toward improvement in insulin tolerance, as hyperinsulinemia drives insulin resistance and obesity." (PMID 34685781, 2021). "Indeed, it has been recently suggested that in human subjects excess LCACs can be converted to metabolites as diacylglycerol and ceramides and activate stress kinases, thus disturbing insulin signaling and contributing to insulin resistance." (PMID 34383825, 2021). "In addition, the serum insulin level and homeostatic model assessment of insulin resistance (HOMA-IR) index were significantly lower in GHR KO pigs." (PMID 34803486, 2021). "These new data indicate that the alteration of FA oxidation is the cause of metabolic disorders-related insulin resistance in skeletal muscle unlike what is described for insulin secretion by pancreatic β-cells." (PMID 33844166, 2021). "Moreover, the basal ANGPTL6 level correlates with insulin resistance as well as fasting insulin levels (Table A2)." (PMID 33668309, 2021). "Because eWAT and prWAT are linked to insulin resistance and type 2 diabetes, the reduced size of WAT from increased lipolysis triggered by Gdf3 reduction might account for the improved insulin sensitivity in Brd4-CKO mice." (PMID 33830083, 2021). "Indeed, insulin resistance is correlated with various inflammatory responses which play a crucial role in the decline of insulin sensitivity." (PMID 34258288, 2021). "We conducted this study in order to verify the hypothesis that treatment with high exogenous insulin doses that indirect refer insulin resistance in the diabetic population, could have more expressed effect on cognitive function." (PMID 34577866, 2021). "Meanwhile, PRKCE could also impairs insulin signaling and its ability to activate glycogen synthesis and inhibit neoglucogenesis, resulting in insulin resistance." (PMID 35140684, 2021). "Insulin resistance (IR) is defined as a state in which normal concentrations of insulin produce a less-than-normal biological response in insulin-sensitive tissues (e.g., liver, muscle, adipose tissues) to the metabolic actions of insulin." (PMID 36338381, 2021). "Adiponectin can increase insulin sensitivity and improve insulin resistance in diabetic patients." (PMID 34322993, 2021). "From the results, it was determined that CDAHFD‐0.1 induced insulin sensitivity, while CDAHFD‐0.6 induced insulin resistance, and the different changes were induced regarding sensitivity to insulin by CDAHFD‐0.1 and CDAHFD‐0.6 as early as 8 weeks and continued thereafter." (PMID 34390210, 2021). "Our findings that FAO leading to adverse pregnancy outcome is associated with decreased insulin secretion rather than insulin resistance is different from the European data that GDM women with high insulin resistance showed poor pregnancy outcomes." (PMID 34893662, 2021). "It has been shown that systemic insulin resistance and hyperinsulinemia might reduce brain insulin levels through a compensatory mechanism involving insulin receptors’ reduction in the blood-brain barrier." (PMID 33597002, 2021). "In addition, metabolic assessment (blood glucose, insulin levels, insulin resistance (via the homeostatic model assessment of insulin resistance) and lipid profile) should also be conducted in all children with suspected or diagnosed NAFLD." (PMID 34944730, 2021).